CGAS (cyclic GMP-AMP synthase)
Diseases named in the same sentence as CGAS in open-access papers (continued):
Sharing a sentence is not in itself a finding about the gene and the disease.
Cognitive impairment (16 papers, 2022 to 2026). Abnormal cognition is characterized by deficits in thinking, reasoning, or remembering. "Moreover, treatment of a novel small molecule cGAS inhibitor demonstrated efficacy against synapse loss and cognitive deficits in tauopathy mice." (PMID 38774266, 2024). "Thus, pharmacological inhibition of cGAS protected against synapse loss and cognitive deficits in the P301S tauopathy model, likely via enhancing the MEF2C transcriptional network and associated cognitive resilience." (PMID 37095396, 2023). "By establishing an inducible, microglia‐specific cGAS knockout mouse model in the 5xFAD background, we investigated the effects of cGAS on Aβ pathology, as well as Aβ accumulation‐induced cognitive impairment." (PMID 39908354, 2025). "In contrast, depletion of PQBP1 markedly attenuates the recruitment of cGAS and NF-κB-dependent transcription of inflammation genes, thus mitigating inflammation in the brain and cognitive impairment." (PMID 40038765, 2025). "The later, together with the activation of the cGAS–STING signaling pathway by accumulated DNA, causes neuron dysfunction and loss, neuroinflammation and cognitive deficits." (PMID 39095921, 2024). "cGAS deletion alleviated cognitive impairment and reduced Aβ pathology and ISG expression in the hippocampus." (PMID 37941028, 2023). "Knockout of cGAS in 5×FAD mouse largely protected from cognitive impairment and Aβ pathology, highlighting cGAS-STING as an important therapeutic target for AD." (PMID 37433768, 2023). "To explore the impact of cGAS-/- on HFD-induced cognitive impairment across sex, we performed puzzle box testing." (PMID 37206668, 2023). "In a high-fat diet obese mouse model for prediabetes and cognitive impairment, increased expression of cGAS and STING was noted in the hippocampus as early as four days following high-fat diet feeding." (PMID 37175853, 2023). "Our study in naturally aged mice demonstrates that activation of cGAS–STING signalling is an essential contributor to the ageing-related type I IFN response in microglia to direct neuronal loss and cognitive impairment." (PMID 37532932, 2023). "We further characterized a brain-permeable cGAS inhibitor and showed that pharmacological inhibition of cGAS protected against cognitive impairment in P301S tauopathy mice and enhanced neuronal MEF2C transcriptional network." (PMID 37941028, 2023). "In contrast, genetic deletion of the cGAS gene improved neuroinflammation and reduced cognitive impairment." (PMID 37998717, 2023). "Genetic deletion of the cGAS gene in 5xFAD mice protected against cognitive impairment and ameliorated Aβ pathology and neuroinflammation." (PMID 37175853, 2023). "Hence, these reports point to the cGAS-STING-IFN-I axis as a key driver of tau pathology and associated cognitive impairment." (PMID 38774266, 2024). "The authors further created a tamoxifen-induced, microglia-specific cGAS activation mouse model and showed that tamoxifen injection resulted in cognitive impairment, increased brain inflammatory gene expression, IFN-I response, and a reduction in hippocampal neuron density." (PMID 37941028, 2023). "As cGAS/STING-induced inflammation is thought to contribute to cognitive impairment, we hypothesized that cGAS knockout mice would have reduced microglial activation, lower inflammation, and thus be partially protected from HFD-induced cognitive decline." (PMID 37206668, 2023). "The innate immune cGAS/STING pathway is dysregulated in cognitive impairment and neurogenerative disease and by responding to excess saturated fatty acids may connect metabolic dysfunction to inflammation in the CNS." (PMID 36248795, 2022). "Using an inducible, microglia‐specific cGAS knockout mouse model in the 5xFAD background, we demonstrated that deleting microglial cGAS at the onset of amyloid‐β (Aβ) pathology profoundly restricts plaque accumulation and protects mice from Aβ‐induced cognitive impairment." (PMID 39908354, 2025).
Cognitive impairment (continued). "Thus, cGAS/STING may be a mechanistic “bridge” between metabolic dysfunction and cognitive impairment, making murine models that specifically target cGAS/STING of great interest in understanding this connection." (PMID 37206668, 2023). "Activation of cGAS-STING pathway alone shifted microglia to an aging and disease-related state, resulting in compromised neuronal survival and cognitive impairment." (PMID 37941028, 2023). "The innate inflammatory cGAS/STING (cyclic GMP-AMP/stimulator of interferon genes) pathway is an emerging target of interest in both metabolic dysfunction and cognitive impairment." (PMID 37206668, 2023). "By contrast, inhibition of cGAS enhanced the MEF2C transcriptional network and rescued cognitive deficits despite similar tau pathology, enhancing cognitive resilience." (PMID 37095396, 2023). "Here we found that HFD-fed male, and not HFD-fed female, cGAS-/- mice have cognitive deficits in the tunnel task compared to their SD-fed counterparts." (PMID 37206668, 2023). "In addition, the cGAS-STING signaling pathway plays a crucial role in hippocampal microglia pyroptosis, which may contribute to the cognitive deficits observed in the TL group." (PMID 40918734, 2025). "Interestingly, HFD fed male cGAS-/- mice displayed cognitive impairment relative to SD fed males, whereas HFD females were not significantly different from their SD controls." (PMID 37206668, 2023). "Instead, female cGAS-/- fed a HFD did not have significant differences in their puzzle box performance relative to female cGAS-/- animals fed SD, indicating that they may be protected from HFD-induced cognitive impairment." (PMID 37206668, 2023).
glioblastoma (16 papers, 2018 to 2026). The most malignant astrocytic tumor (WHO grade IV). "This study reveals the immunosuppressive effects of PTEN loss in glioblastoma tumours via the cGAS-STING pathway." (PMID 38214828, 2024). "We examined the co‐expression of PRKDC and MB21D1 (encoding cGAS) in glioblastoma tissue samples from the CGGA transcriptomic database." (PMID 36574362, 2023). "Using this framework to inform rational sequential therapy in preclinical models, we show that immunomodulation in response to genomic stress after DNA-PKcs inhibition and RT primes glioblastoma for response to cGAS/STING activation." (PMID 42281979, 2026). "The cGAS/STING pathway is relatively unexplored within glioblastoma: however, some evidence suggests its activation enhances anti-tumour immune response and T cell priming." (PMID 38227740, 2024). "To confirm the physiological relevance of our findings that indicate that cGAS expression impairs early tumorigenesis, we first performed a meta‐analysis of glioblastoma tumors, using the GlioVis database." (PMID 36574362, 2023). "Considering that DNA‐PK can elicit type I IFN responses in absence of cGAS, we next interrogated the impact of co‐expressing DNA‐PKcs and cGAS in glioblastoma cells." (PMID 36574362, 2023). "Here, we used glioblastoma cells that show undetectable cGAS levels to address if alternative DNA detection pathways can promote pro‐inflammatory signaling." (PMID 36574362, 2023). "Furthermore, we tested the inducible expression of cGAS in glioblastoma cell lines GBM39KT (ecDNA+) and GBM39HSR (ecDNA−)." (PMID 41509453, 2026). "As we did not study the response of immune cell populations towards ATRi treated glioblastoma cells, it is uncertain whether the upregulation of cGAS/STING may activate adequate T cell populations within the brain." (PMID 38227740, 2024). "We further show that the cooperation between DNA‐PK and cGAS favors the expression of chemokines that promote macrophage recruitment in the tumor microenvironment in a glioblastoma model, a process that impairs early tumorigenesis but correlates with poor outcome in glioblastoma patients." (PMID 36574362, 2023). "We next questioned whether the synergy between cGAS and DNA‐PK could have an impact on glioblastoma tumor immunogenicity." (PMID 36574362, 2023). "Consistent with Pan‐cancer analysis, analysis of patient survival showed that higher MB21D1 expression led to worst patient survival as compared to patients with low MB21D1 expression, supporting that expression of cGAS is a poor outcome marker in glioblastoma." (PMID 36574362, 2023). "The effect of glioblastoma standard treatment and ATRi was also examined across genes involved in immune pathways, such as the immunoproteasome, MHC-I signalling and cGAS/STING pathway." (PMID 38227740, 2024). "Interestingly, cGAS and DNA-PKcs levels increased with higher glioblastoma grade and correlated with poor outcomes leading the authors to speculate that long-term, sustained activation of this axis may lead to chronic inflammation which may promote tumorigenesis." (PMID 39043779, 2024). "In this context, it was observed that the treatment with TTFields led to both AIM2 assembly and activation and the induction of the cGAS-STING pathway, both responsible for the membrane-damaged cell death of glioblastoma cancer stem-like cells derived by patients." (PMID 40002808, 2025). "Therefore, this study aimed to represent the link between PTEN and cGAS-STING activity, a key mediator of inflammation, in tumour samples of glioblastoma patients." (PMID 38214828, 2024). "Yet, high levels of cGAS and STING predict poor prognosis, and recent reports underscore that the presence of a functional cGAS‐STING axis supports tumorigenesis of chromosomally unstable cancers, which is in agreement with our glioblastoma patient data analysis." (PMID 36574362, 2023).
glioblastoma (continued). "This attests to the production of bioactive type I IFNs from glioblastoma cells, where cGAS is not detectable, further indicating that glioblastoma cells possess cGAS‐independent cytosolic dsDNA detection mechanisms." (PMID 36574362, 2023). "Here, we used glioblastoma cells to interrogate how type I IFN responses are initiated in the absence of detectable cGAS." (PMID 36574362, 2023). "The cGAS-STING Signalling Pathway was significantly enriched in gartisertib (−log10 (B-H p-value) = 2.85, z-score = 4.81) and gartisertib+TMZ+RT (−log10 (B-H p-value) = 4.45, z-score = 5.47) treated groups after IPA analysis across the 12 glioblastoma cell lines." (PMID 38227740, 2024). "Second, we tested whether DNA‐PK is responsible for type I IFN responses in the absence of cGAS in glioblastoma cells by treating T98G, Gli4, and GSC9 with the NU7441 DNA‐PKcs inhibitor." (PMID 36574362, 2023). "Reflecting on the various mechanisms of modulating the cGAS-STING pathway in oncology, it is important to realize that in many tissues, the level of STING expression is low, especially in most normal brain cells and human glioblastoma cells (a classic example of an immunologically cold tumor)." (PMID 38139802, 2023). "One research hypothesizes that Tumor Treating Fields (TTFields), approved in combination with adjuvant temozolomide chemotherapy for newly diagnosed glioblastoma (GBM) patients, induced a significant improvement in overall survival after AIM2 and cGAS activation." (PMID 39857785, 2025). "Our examination of two glioblastoma cell lines (U138MG and H4 cells) that naturally do not express STAG2 indicates that both are defective in the cGAS-STING pathway." (PMID 29662124, 2018).
Huntington disease (16 papers, 2020 to 2025). Huntington disease (HD) is a rare neurodegenerative disorder of the central nervous system characterized by unwanted choreatic movements, behavioral and psychiatric disturbances and dementia. "A similar phenomenon has been observed in Huntington’s disease (HD), where cGAS upregulation has been identified in both murine models and human tissues." (PMID 41300248, 2025). "In 2020, a study on the role of cGAS in promoting inflammation and autophagy in huntington disease (HD) mentioned the localization of cGAS in lysosomes in HD-homo striatal cells." (PMID 38515746, 2024). "This is consistent with other findings showing that the cGAS-STING pathway activates the autophagy process through a TANK-binding kinase 1 (TBK1) independent mechanism and that cGAS is a critical regulator of inflammation and autophagy in Huntington’s disease." (PMID 36114513, 2022). "Since cGAS is up-regulated and mediates inflammation in the brain in neurodegenerative disorders like Huntington’s disease, central STING/type I IFN-dependent effects may also be relevant." (PMID 33291536, 2020). "The upregulation of cGAS was observed in the striatum from postmortem Huntington disease (HD) patients, and HD cells showed enhanced inflammatory gene expression and autophagy induction." (PMID 33633744, 2020). "The cGAS/STING pathway might also play a role in accelerated aging and neurodegeneration observed in Huntington’s disease (HD)." (PMID 34659260, 2021).
cervical carcinoma (14 papers, 2019 to 2026). A carcinoma arising from either the exocervical squamous epithelium or the endocervical glandular epithelium. "Methylation in the cGAS gene promoter region has been linked to the risk of cervical precancerous lesions (CPL) and cervical cancer (CC) in a Southern Chinese population." (PMID 39949780, 2025). "A recent study demonstrated that HPV oncoproteins E6 and E7 upregulated topoisomerase I (TOP1) expression to activate the cGAS-PD-L1 pathway, consequently promoting cervical cancer development." (PMID 41142804, 2025). "Cervical cancer is the most prevalent cancer type associated with HPV infection, and a growing body of evidence underscores the critical role of the cGAS-STING signaling pathway in cervical cancer." (PMID 41142804, 2025). "In cervical cancer, IDH3α suppresses the cGAS–STING pathway, impairing the immune response within the tumor microenvironment." (PMID 39949780, 2025). "STING-mediated response was inhibited in cervical cancer cells, as evidenced by the reduction of cGAS, STING, and IFN-β expression." (PMID 41142804, 2025). "A research reported that PIN1 promoted the proliferation and invasion of cervical cancer cells by inhibiting ferroptosis, which was mediated by the inhibition of the cGAS-STING pathway." (PMID 41142804, 2025). "The signal of the cGAS-STING pathway was observed to be decreased in cervical cancer cells, and knocking down STING by siRNA enhanced the cell viability and the migration of cervical cancer cells." (PMID 36769349, 2023). "Importantly, the combination alleviated cisplatin-induced nephrotoxicity, suggesting the potential of Fu/CA NPs in treating cervical cancer by targeting the cGAS-STING pathway." (PMID 41142804, 2025). "Notably, cGAS/STING expression is significantly lower in HPV-positive cervical cancer cells compared to HPV-negative cells." (PMID 39445027, 2024). "Promoter methylation status of cyclic GMP-AMP synthase (cGAS)/mitochondrial antiviral-signaling (MAVS)/tumor necrosis factor receptor-associated factor 3 (TRAF3) in control, cervical precancerous lesion (CPL), and cervical cancer (CC)." (PMID 31803230, 2019). "Association analysis of the promoter methylation level of cyclic GMP-AMP synthase (cGAS)/mitochondrial antiviral-signaling (MAVS)/tumor necrosis factor receptor-associated factor 3 (TRAF3) gene with the risk on cervical precancerous lesion (CPL), and cervical cancer (CC)." (PMID 31803230, 2019). "Increasing evidence has described the role of the cGAS-STING pathway in HPV-related cancers, such as cervical cancer and head and neck squamous cell carcinoma." (PMID 41142804, 2025). "By exploring the roles of cGAS-STING in ovarian, endometrial, and cervical cancers, we will discuss how this pathway contributes to immune surveillance, inflammation, and the tumor microenvironment, offering insights into potential therapeutic targets for improving cancer treatment outcomes." (PMID 39949780, 2025). "Furthermore, we found that inhibition of IDH3α combined with chemoimmunotherapy (cisplatin and programmed cell death ligand 1 (PD-L1) antibodies) activated the cGAS–STING pathway, promoted CD8+ T cell infiltration, and decreased tumor growth in mouse models of cervical cancer." (PMID 36980689, 2023).
Insulin resistance (14 papers, 2020 to 2025). Increased resistance towards insulin, that is, diminished effectiveness of insulin in reducing blood glucose levels. "In contrast, mice with fat-specific DsbA-L overexpression are protected from obesity-induced inflammation and insulin resistance by inhibiting the cGAS-STING pathway." (PMID 41020872, 2025). "The modulation of the cGAS-STING pathway as a means of regulating insulin resistance presents a novel approach to the treatment of type 2 diabetes." (PMID 37915571, 2023). "Emerging data showed that insulin resistance and dysregulation of the cyclic GMP-AMP synthase (cGAS)-stimulator of interferon genes (STING) pathway are the major driving forces for acute pancreatitis and fibrogenesis in NAFP progression." (PMID 36915161, 2023). "Under diabetic conditions, the activation of Peroxisome Proliferator-Activated Receptor Alpha (PPARα) can attenuate the cGAS-STING signaling pathway, leading to reduced inflammation and insulin resistance." (PMID 41020872, 2025). "Studies have demonstrated that IRF3, part of the cGAS-STING pathway, plays a protective role against diet-induced hepatic insulin resistance." (PMID 39669992, 2024). "A growing body of evidence has shown that the cGAS-STING pathway was also activated by host DNA, which aberrantly localized in the cytosol, contributing to increased sterile inflammation, insulin resistance, and the development of NAFLD." (PMID 35235096, 2023). "The cGAS-STING pathway is activated by host DNA that is aberrantly located in the cytosol, which contributes to enhanced inflammation-mediated insulin resistance." (PMID 37223012, 2023). "The cGAS‒STING pathway is highly enriched in immune cells in metabolic tissues including the liver and adipose tissue, and activation of this pathway may promote inflammation, leading to a detrimental microenvironment in the tissues that causes insulin resistance or hepatosteatosis." (PMID 34665236, 2021). "Conversely, reducing mtDNA release by adipocyte-specific overexpression of DsbA-L alleviated HFD-induced activation of the cGAS‒STING pathway and protected mice against HFD-induced inflammation and insulin resistance." (PMID 34665236, 2021). "If the gut microbial DNA carried by these exosomes activates the cGAS-STING pathway, it could trigger an inflammatory response, impair insulin signaling, and promote the development of insulin resistance." (PMID 41020872, 2025). "This is supported by recent research demonstrating that cGAS‐STING can amplify NLRP3 activation in response to cytosolic DNA accumulation in conditions like intervertebral disc degeneration, acute liver injury, and insulin resistance." (PMID 40522023, 2025). "The deletion of DsbA-L could impair mitochondrial functions and active the cyclic GMP-AMP synthase (cGAS)-stimulator of interferon genes (STING) signaling pathway, exacerbating inflammation and insulin resistance." (PMID 39616329, 2024). "The cGAS-cGAMP-STING pathway plays an important role in mediating inflammatory responses and may have a significant role in insulin resistance in T2DM." (PMID 36139069, 2022). "Notably, the expression of cGAS, STING, and TBK1 is elevated in adipocytes, which may contribute to sterile inflammatory response, insulin resistance, and hyperglycemia." (PMID 37915571, 2023). "cGAS-STING signaling pathway is a crucial regulator of immune responses and plays an important role in glucolipid metabolic disorders and was found to be activated in the animals fed a high-fat diet, and its gene silencing reversed metabolic dysfunction, insulin resistance, and inflammation." (PMID 36915161, 2023).